PRR5-ARHGAP8 (PRR5-ARHGAP8 readthrough)
Gene: Protein-coding gene on chromosome 22 (44,702,233 to 44,862,706, forward strand). Ensembl gene ENSG00000248405.
Genetic constraint (gnomAD): Loss-of-function variants: 79 observed, 60.42 expected, observed/expected ratio (o/e) 1.31, 90% interval 1.09 to 1.58. The synonymous counts are far from expectation, so gnomAD's model fits this gene poorly and the ratio says little. Missense variants: 1,084 observed, 713.63 expected, observed/expected ratio (o/e) 1.52, 90% interval 1.44 to 1.6. Synonymous variants: 455 observed, 309.65 expected, observed/expected ratio (o/e) 1.47, 90% interval 1.36 to 1.59.